NTNG2 (netrin G2)
Description:
Involved in controlling patterning and neuronal circuit formation at the laminar, cellular, subcellular and synaptic levels. Promotes neurite outgrowth of both axons and dendrites.
Synonyms: KIAA1857; LMNT2; NetrinG2; LHLL9381; NEDBASH; NTNG1; bA479K20.1
Tractability: Small molecule: it has a binding pocket of medium quality. Antibody: UniProt places it where antibodies can reach, with high confidence; its Gene Ontology location is reachable by antibodies, with high confidence; UniProt predicts a signal peptide or a membrane-spanning region. PROTAC: its protein half-life has been measured.
Gene: Protein-coding gene on chromosome 9 (132,161,020 to 132,244,528, forward strand). Ensembl gene ENSG00000196358.
Subcellular location: Cell membrane
Subcellular location (Human Protein Atlas): Vesicles; Plasma membrane
Pathways (Reactome):
Metabolism of proteins: Post-translational modification: synthesis of GPI-anchored proteins
Gene Ontology:
Molecular function: protein binding; cell-cell adhesion mediator activity
Biological process: axonogenesis; regulation of neuron migration; regulation of neuron projection arborization; regulation of neuron projection development; synaptic membrane adhesion; modulation of chemical synaptic transmission; postsynaptic specialization assembly; regulation of presynapse assembly
Cellular component: plasma membrane; extracellular region; axon; glutamatergic synapse; presynaptic active zone membrane; Schaffer collateral - CA1 synapse
Genetic constraint (gnomAD): Loss-of-function variants: 15 observed, 46.1 expected, observed/expected ratio (o/e) 0.33, 90% interval 0.22 to 0.5. The upper end of that interval is the gene's LOEUF score, 0.5, which puts it in group 2 of 6, group 1 being the genes least tolerant of losing a copy. Missense variants: 574 observed, 734.96 expected, observed/expected ratio (o/e) 0.78, 90% interval 0.73 to 0.84. Synonymous variants: 305 observed, 304.32 expected, observed/expected ratio (o/e) 1, 90% interval 0.91 to 1.1.
Homologues: Orthologues: chimpanzee NTNG2 (99% identical), macaque NTNG2 (99% identical), dog NTNG2 (96% identical), pig NTNG2 (95% identical), rat Ntng2 (94% identical), mouse Ntng2 (94% identical), guinea pig NTNG2 (93% identical), tropical clawed frog ntng2 (75% identical), rabbit NTNG2 (71% identical), zebrafish ntng2a (67% identical), zebrafish ntng2b (28% identical). Paralogues in human: NTNG1 (57% identical), LAMC1 (29% identical), LAMA3 (29% identical), LAMB1 (29% identical), LAMB2 (28% identical), LAMC3 (28% identical), LAMA5 (28% identical), LAMB4 (28% identical), LAMA1 (28% identical), LAMA2 (26% identical), NTN1 (25% identical), NTN4 (25% identical), and 15 more.
Diseases named in the same sentence as NTNG2 in open-access papers:
NTNG2 is named in the same sentence as 27 diseases in open-access papers, as found by Europe PMC text mining. Sharing a sentence is not in itself a finding about the gene and the disease. The quoted sentences say what the papers report.
schizophrenia (4 papers, 2013 to 2024). A major psychotic disorder characterized by abnormalities in the perception or expression of reality. "Among these, several schizophrenia-associated genes were also detected, including NTNG2, which is known to be involved in neurodevelopmental disorders and GRIN3A, a gene that encodes NMDA receptor subunits in neuronal nuclei." (PMID 38648100, 2024). "NTNG1 and NTNG2 are associated with schizophrenia and bidirectional affective disorder." (PMID 32251318, 2020). "Studies on the correlation of gene polymorphisms in schizophrenia revealed that NTNG1 and its paralogues for NTNG2 gene may be related to the pathophysiology of schizophrenia." (PMID 34814929, 2021).
epilepsy (3 papers, 2013 to 2022). A brain disorder characterized by episodes of abnormally increased neuronal discharge resulting in transient episodes of sensory or motor neurological dysfunction, or psychic dysfunction. "Levels of netrin receptors and netrin G2 are regulated by psychostimulant drugs, endocannabinoid receptor antagonists, and epilepsy-induced activity." (PMID 24065916, 2013). "Netrin G2 levels are also elevated in the cortex of epileptic patients and mice, indicating that netrin G2 expression may be regulated by alterations in neuronal activity induced by epilepsy." (PMID 24065916, 2013).
bipolar disorder (2 papers, 2013 to 2020). A disorder of the brain that causes unusual shifts in mood, energy, activity levels and the ability to carry out day-to-day tasks. "Single nucleotide polymorphisms or abnormal expression of NTNG1 and NTNG2 are related to psychiatric disorders such as autism, Rett syndrome, schizophrenia, and bipolar disorder in human and murine models." (PMID 33520982, 2020). "The levels of NTNG1 mRNA, especially isoform G1c, and NTNG2 are decreased in patients with bipolar disorder." (PMID 33520982, 2020). "However, the same group later reported elevations of netrin G1d and G1f isoforms and of netrin G2 in patients with bipolar disorder, indicating that an alteration of netrin G1 levels is critical for susceptibility to the disease." (PMID 33520982, 2020).
developmental delay (2 papers, 2019 to 2020). "Several mutations in NTNG2 have been described and they cause global developmental delay, hypotonia, secondary microcephaly, Rett-like phenotype, and autistic features." (PMID 32762776, 2020).
thyroid cancer (2 papers, 2020 to 2024). "Although NTNG2 is not well reported in AML, it is associated with the development of other cancers, such as breast and thyroid cancer." (PMID 38807380, 2024). "The transcription of NTN1 and NTNG2 is positively regulated by MYC in THCA, suggesting that NTN1 and NTNG2 may also participate in the development of thyroid carcinoma." (PMID 32251318, 2020).
Achalasia (1 paper, 2022). A disorder of esophageal motility characterized by the inability of the lower esophageal sphincter to relax during swallowing and by inadequate or lacking peristalsis in the lower half of the body of the esophagus. "If there is abnormal synaptic remodeling caused by the corresponding upregulation of NTNG2 expression in the LES, there may be evidence that high expression of NTNG2 is associated with idiopathic achalasia." (PMID 35509690, 2022).
Anxiety (1 paper, 2016). Intense feelings of nervousness, tension, or panic often arise in response to interpersonal stresses. "For anxiety evaluation tasks, it is especially interesting that netrin-G1 KO mice demonstrated reduced anxiety in the EPM test, but not the OF test, whereas netrin-G2 KO mice exhibited abnormalities in both tests." (PMID 26746425, 2016).
breast carcinoma (1 paper, 2020). "The transcription of NTNG2 in breast cancer is positively regulated by ETS1 (r = 0.2971), suggesting that NTNG2 may be related to the development of breast cancer." (PMID 32251318, 2020).
Intellectual disability (1 paper, 2019). "In summary, our results implicate rare bi-allelic missense NTNG2 variants in the pathobiology of a neurodevelopmental disorder consisting of severe intellectual disability, autistic features, and motor impairment." (PMID 31668703, 2019). "An in vitro study of variants in the histone demethylase KDM5C (Lysine demethylase 5C [MIM: 314690]), which is known to cause intellectual disability, showed that NTNG2 seemed to be important in mediating effects on neurite growth and length; these results are consistent with our findings here." (PMID 31668703, 2019). "NTNG2 should be considered in the clinical evaluation of children with severe intellectual disability and neuropsychiatric symptoms." (PMID 31668703, 2019). "In fact, given the profound finding of intellectual disability in the individuals presented here, it is intriguing that NTNG2 expression is enriched in the human claustrum, an enigmatic brain region posited to play a role in the integration of conscious perception." (PMID 31668703, 2019). "In addition to identification by exome sequencing, it will be important to add NTNG2 to clinical gene-panel tests for intellectual disability given the marked yet variable clinical phenotype." (PMID 31668703, 2019).
multiple sclerosis (1 paper, 2021). A progressive autoimmune disorder affecting the central nervous system resulting in demyelination. "In addition, based on the bioinformatics analysis of the pediatric onset of multiple sclerosis, genes such as NTNG2 were found to be nodes of the network, and the expression of some miRNAs were significantly correlated with brain volume." (PMID 34814929, 2021).
prostate carcinoma (1 paper, 2020). A carcinoma that arises from epithelial cells of the prostate gland. "Highly expressed NTN3 and NTNG2 cells are sensitive to these drugs, suggesting NTN3 and NTNG2 may be involved in N-Myc-related pathways and affect androgen-independent prostate cancer development." (PMID 32251318, 2020).
Stroke (1 paper, 2019). Sudden impairment of blood flow to a part of the brain due to occlusion or rupture of an artery to the brain. "Furthermore, four upregulated candidates were addressed in this study as potential stroke-induced growth-promoters: Sema6a, Ntng2, GDF7, and TGF-β1." (PMID 30962276, 2019). "For three upregulated genes of the late phase, Sema6a, Ntng2, and TGF-β1, the potential to overcome spinal cord extract mediated growth-inhibition was shown in an in vitro neurite outgrowth assay, suggesting their role as growth-promoters in the spinal GM after stroke." (PMID 30962276, 2019).
cancer (5 papers, 2019 to 2024). A tumor composed of atypical neoplastic, often pleomorphic cells that invade other tissues. "Here we find that the expression or methylation of NTNG1 and NTNG2 is associated with survival and other clinical parameters of more than 10 types of cancer." (PMID 32251318, 2020). "It is worth noting that the mutations and potential mirRNA targeting of NTNG1 and NTNG2 in cancer exhibit rates that are much higher than those predicted for NTN1 and NTN4." (PMID 32251318, 2020). "NTNG2 may be considered as a potential diagnostic biomarker and therapeutic target in cancers." (PMID 34571936, 2021). "Additionally, the participation of NTNG1 and NTNG2 in various cancers shows their potential for use as new tumor markers and therapeutic targets." (PMID 32251318, 2020). "In addition to the studies that are published about NTNG2 involving the function in brain development and behavior, a couple of studies have investigated NTNG2 outside of the nervous system and related to cancer." (PMID 30923634, 2019). "An unexpected finding in this study was the identification of the potential cancer biological significance of NTNG1 and NTNG2." (PMID 32251318, 2020). "EQTL affects the expression of NTNG2 in BRCA, THCA, and other cancers." (PMID 32251318, 2020). "No research has reported on the function of the netrin-G2 protein in these cancers, and experiment to determine the functional consequences has to be executed before any statements about possible therapeutically potentials can be made." (PMID 30923634, 2019).
tumor (4 papers, 2020 to 2025). "We not only reveal the important role of the netrin family in the development of endocrine-related tumors and sex hormones targeting organ tumors, but suggest that NTNG1 and NTNG2 may be potential tumor diagnostic markers and treatment targets that warrant future in-depth systematic research." (PMID 32251318, 2020). "These contain known cancer-testis antigen genes (MEGA5, MEGA1, TEX15, PNMA5 and ROR1) and a number of new candidate genes (PAX2, NTN4, NTNG2 and PDE10A), these genes can be used as tumour markers or potential therapeutic targets with some clinical value." (PMID 37994961, 2023). "Perineural spread, associated with mutations in adhesion and axon guidance genes such as NTNG2 and RELN, enables tumor extension along nerve sheaths, often without overt mass formation." (PMID 41463022, 2025).
neurodevelopmental disorder (3 papers, 2019 to 2024). A behavioral and cognitive disorder with onset during the developmental period that involves impaired or aberrant development of intellectual, motor, or social functions. "We have identified 16 individuals (from seven unrelated families) who have ultra-rare bi-allelic variants in NTNG2 and who present with shared clinical features of a neurodevelopmental disorder." (PMID 31668703, 2019).
neurological disorders (1 paper, 2021). "Therefore, we speculate that NTNG2 and NTNG1 may play a role in neurological disorders." (PMID 34814929, 2021).
NTNG2 also shares sentences with these, for which no sentence is quoted: autism (1 paper); autism spectrum disorder (1); deafness (1); depression (1); early infantile epileptic encephalopathy (1); glioblastoma (1); gout (1); juvenile amyotrophic lateral sclerosis (1); microcephaly (1); neurodegenerative disease (1); psychiatric disorder (1).